CCDC26 (CCDC26 long non-coding RNA)
Diseases named in the same sentence as CCDC26 in open-access papers (continued):
Sharing a sentence is not in itself a finding about the gene and the disease.
hematologic malignancies (1 paper, 2025). "Notably, CCDC26 overlaps the BENC (blood enhancer cluster), a distal regulatory element that physically contacts the MYC promoter and is implicated in MYC activation via enhancer hijacking mechanisms in multiple hematologic malignancies." (PMID 41509392, 2025).
CCDC26 also shares sentences with these, for which no sentence is quoted: asthma (2 papers); acute lymphoblastic leukemia (1); acute monocytic leukemia (1); astrocytoma (1); brain tumors (1); cholangiocarcinoma (1); cleft lip (1); depression (1); diffuse intrinsic pontine glioma (1); lymph node metastasis (1); melanoma (1); multiple myeloma (1); neuroblastoma (1); oligodendroglioma (1); osteoarthritis (1); prostate carcinoma (1); schizophrenia (1).